YJU2B (YJU2 splicing factor homolog B)
Description:
May be involved in mRNA splicing.
Synonyms: CCDC130; MGC10471
Tractability: PROTAC: ubiquitination databases record sites on it.
Gene: Protein-coding gene on chromosome 19 (13,731,752 to 13,763,298, forward strand). Ensembl gene ENSG00000104957.
Subcellular location: Nucleus
Subcellular location (Human Protein Atlas): Vesicles
Gene Ontology:
Molecular function: protein binding
Biological process: response to virus; mRNA cis splicing, via spliceosome; mRNA splicing, via spliceosome
Cellular component: nucleus; post-mRNA release spliceosomal complex; U2-type spliceosomal complex
Genetic constraint (gnomAD): Loss-of-function variants: 18 observed, 39.07 expected, observed/expected ratio (o/e) 0.46, 90% interval 0.32 to 0.68. The upper end of that interval is the gene's LOEUF score, 0.68, which puts it in group 2 of 6, group 1 being the genes least tolerant of losing a copy. Missense variants: 538 observed, 554.36 expected, observed/expected ratio (o/e) 0.97, 90% interval 0.9 to 1.04. Synonymous variants: 246 observed, 221.65 expected, observed/expected ratio (o/e) 1.11, 90% interval 1 to 1.23.
Homologues: Orthologues: chimpanzee YJU2B (99% identical), dog YJU2B (87% identical), pig YJU2B (87% identical), guinea pig YJU2B (80% identical), mouse Yju2b (78% identical), rat Yju2b (77% identical), tropical clawed frog yju2b (62% identical), zebrafish yju2b (56% identical), Drosophila melanogaster CG15084 (41% identical), Caenorhabditis elegans ZK1307.9 (39% identical). Paralogues in human: YJU2 (24% identical).
Diseases named in the same sentence as YJU2B in open-access papers:
YJU2B is named in the same sentence as 3 diseases in open-access papers, as found by Europe PMC text mining. Sharing a sentence is not in itself a finding about the gene and the disease.
YJU2B shares sentences with these, for which no sentence is quoted: atherosclerosis (1 paper); lymphoma (1); ovarian tumors (1).